ASPG (asparaginase)
Diseases named in the same sentence as ASPG in open-access papers (continued):
Sharing a sentence is not in itself a finding about the gene and the disease.
leukemia (continued). "Extensive clinical data and studies have demonstrated that asparaginase chemotherapy in children with leukaemia and lymphoma can improve remission and overall survival rates." (PMID 39439952, 2024). "Exploration of the dual action of asparaginase against both asparagine and glutamine highlights its potential utility across different leukaemia subtypes." (PMID 39766036, 2024). "In Leukemia elevated asparagine has been found to be positively correlated with poor prognosis for this reason some treatments focus on asparaginase activation." (PMID 37633054, 2023). "The most successful example of this approach is asparaginase, an enzyme that depletes asparagine, which is used against leukemia." (PMID 37762044, 2023). "A more recent preclinical study showed that the administration of 20,000 U/kg asparaginase alone for 14 days insufficiently produced leukemia cytotoxicity and required additional glutaminase activity for both asparagine synthetase-positive and -negative mice." (PMID 35565690, 2022). "Increased production of glutamine synthetase is suspected to reduce the efficacy of L-asparaginase, which is a chemotherapeutic agent that depletes glutamine and asparaginase, amino acids that are essential for leukemic cell survival, from the leukemia niche." (PMID 35565219, 2022). "In the late 1960's E. coli derived asparaginase was first incorporated into the treatment of malignancies, primarily lymphoma and leukemia, demonstrating dose dependent remissions." (PMID 35844739, 2022). "Our findings with pigs, reports from clinical studies, and dogs treated for lymphoma or leukemia led us to propose a model for asparaginase-induced hyperammonemia that includes two phases." (PMID 35997335, 2022). "Asparaginase catalyzes the hydrolysis of the asparagine into aspartic acid and ammonia and has been used in the treatment of leukemia." (PMID 35734601, 2022). "Corticosteroids and asparaginase used in the treatment of leukemia and lymphoma are thought to have effects on glucose metabolism." (PMID 35073984, 2022). "The selective dependency of acute lymphoblastic leukemia cells on asparagine led to the routine clinical use of recombinant asparaginase to reduce asparagine levels in the blood, which leads to the death of leukemia cells that are auxotrophic for asparagine." (PMID 33540663, 2021). "TA inhibition of protein synthesis is of particular interest because Asparaginase, which depletes asparagine and glutamine, is in clinical use against leukemia and functions in part by suppressing protein synthesis and by inhibiting mTORC1/S6K1 signaling." (PMID 35095503, 2021). "In accordance to this, previous studies showed that autophagy inhibition enhanced the antitumor effects of daunorubicin, dasatinib, and asparaginase in leukemia models." (PMID 33923896, 2021). "Inhibition of GCN2, for example, reduced the expression of asparagine synthase in leukemia cells and thereby greatly enhanced their sensitivity towards asparagine depletion by asparaginase treatment, both in vitro and in vivo." (PMID 33540663, 2021). "Asparaginase is integral to treatment of leukaemia worldwide, demonstrating the feasibility of clinical treatments by enzymatic amino acid depletion." (PMID 30578463, 2019). "Pharmacokinetic sampling on leukemia bearing mice demonstrated both asparaginase and dexamethasone concentrations were within clinically relevant ranges." (PMID 31059548, 2019). "Asparaginase is a key component in leukemias and lymphomas treatment protocols and is suggested as a treatment for other malignancies in which an amino acid depletion strategy is indicated." (PMID 35582721, 2019). "Whatever the mechanisms, because there are significant differences between the death induced in lymphoblasts by arginase and asparaginase, arginase has the potential to be used as an alternative therapy for asparaginase-resistant leukaemia." (PMID 30578463, 2019).
leukemia (continued). "Taken together our data suggest that ASPG, combining different enzymatic activities, should be considered a promising anti-cancer agent for inhibiting the growth of leukemia cells." (PMID 28542249, 2017). "Asparaginase has been reported to be effective in the treatment of various leukemia and several malignant solid cancers." (PMID 29207624, 2017). "The mutant shows completely preserved asparaginase and glutaminase activities, long-term storage stability, improved thermal parameters, and outstanding resistance to proteases derived from leukaemia cells." (PMID 29101342, 2017). "Testing the effect of ASPG on leukemia cell lines, a significant cytotoxicity of recombinant ASPG was found." (PMID 28542249, 2017). "Asparagine is essential for the proliferation of numerous types of cancer, and extracellular asparaginase therapy has been effectively used for treating low-ASNS-expressing leukemia." (PMID 28811348, 2017). "Asparaginase is an enzyme that has been commonly used in treatment protocols for leukemia for over 30 years." (PMID 23365669, 2013). "In five cases, leukemia preceded T1DM, with two cases linked to asparaginase-induced pancreatitis." (PMID 42216215, 2026). "Correspondingly, in a syngeneic murine leukemia model, the efficacy of asparaginase, a key enzyme in leukemia treatment that hydrolyzes asparagine and glutamine, was impaired in the presence of adipose-rich TME, which provides aa to the ALL, thus promoting leukemia development." (PMID 39518143, 2024). "Additionally, we investigate the effect of asparaginase treatment on glutamine levels in leukemia, aiming to understand the metabolic consequences of leukemia therapies." (PMID 39050845, 2024). "Given the significance of asparaginase in treating paediatric haematological malignancies, the decision to reintroduce asparaginase should be mainly based on its effectiveness in combating leukaemia, even in children with severe AAP." (PMID 39439952, 2024). "The success of asparaginase in the treatment of leukemia has demonstrated the effectiveness of amino-acid deprivation against certain types of cancer, and revealed the hopeful prospect of native bacterial enzymes being developed into therapeutic agents for humans." (PMID 37762044, 2023). "Asparaginase is a chemotherapy regimen that is commonly used in leukemia which could lead to similar ocular manifestations." (PMID 37073201, 2023). "Moreover, a metabolic analysis of 19 leukemia cells and 26 leukemia patients proved that cancer cells of lower mitochondrial respiration and glycolytic function are more sensitive to asparaginase therapy than higher glycolytic cells." (PMID 35565690, 2022). "Since we noticed a significant reduction in fibrinogen (FBG) plasma levels even before the first ASP dose, we aim to assess the levels of FBG during induction treatment and explore if the FBG fall correlated with therapies other than asparaginase and/or specific leukemia biological features." (PMID 35407383, 2022). "Furthermore, Hinze and colleagues showed that GSK3α inhibition profoundly sensitized drug-resistant leukemias to asparaginase by phenocopying a Wnt pathway activation signal." (PMID 35710782, 2022). "Indeed, E. coli-derived asparaginase is used in food manufacturing to reduce levels of the human carcinogen acrylamide and clinically to treat leukemia and lymphoma patients." (PMID 35916501, 2022). "While confounding factors such as concomitant active leukemia, glucocorticoid use, and indwelling central catheters exist, the known disruption of protein synthesis as a result of asparaginase effect on the proteins involved in the coagulation cascade and fibrinolysis is an established mechanism." (PMID 35844739, 2022). "Asparaginase is an enzyme used to treat leukemia and to reduce carcinogenic compounds in food." (PMID 34789157, 2021). "In this setting, switching to an alternative form of asparaginase may benefit to maintain leukemia treatment efficacy." (PMID 34711008, 2021).
leukemia (continued). "Recent studies revealed that asparaginase could be used as a chemotherapeutic agent against not only ALL but also other types of leukemia and several malignant solid cancers." (PMID 29207624, 2017). "As aspartate is a biosynthetic precursor to asparagine, inhibition of aspartatesynthesis could be usefully potentiated by combination with asparaginase treatment,which is a long-established therapy for leukemia." (PMID 25749035, 2015). "Also, patients with a history of NHL and leukemia, treatment with antineoplastic antibiotics, antimetabolites, asparaginase and intrathecal therapy were less prone to develop HT and thyroid nodules." (PMID 25241607, 2014). "One exception may be the treatment with asparaginase used in leukemia and lymphoma treatment protocols." (PMID 25317335, 2014). "No predisposing risk factors, dose effect, leukemia risk group, blood glucose level, gender, age, or preparation of asparaginase correlate with magnitude of TG increase." (PMID 25405049, 2014). "However, studies could demonstrate that ASNS expression and asparaginase response are poorly correlated in human leukemia cells." (PMID 37686063, 2023). "Moreover, our data show that usage of steroids concurrently with asparaginase might increase the risk of VTE, more so for leukemia patients." (PMID 34987942, 2021). "However, recent study showed that asparaginase exhibited significant cytotoxicity of ASNS-positive cancer cells including K562, SR leukemia cells, and this anticancer activity might due to the glutaminase activity of asparaginase." (PMID 25738356, 2015). "Canine lymphomas appeared to be particularly susceptible to arginase, and in contrast to asparaginase - an enzyme commonly used in the treatment of human leukemia and canine lymphoma - no canine lymphomas were able to recover following just 3 days of arginase treatment." (PMID 23365669, 2013). "In leukemia, inhibition of SOD2 sensitizes cells to asparaginase treatment, demonstrating its therapeutic potential." (PMID 40131931, 2025). "Leukemia drugs like MTX affect folate metabolism, while asparaginase disrupts protein synthesis, exacerbating these issues." (PMID 40548495, 2025). "Inspired by these findings, we have decided to further promote this approach through its application to enhance the therapeutic potential of asparaginase drugs (ASP), which are used in the treatment of leukemia." (PMID 39125158, 2024). "In ALL, numerous studies have reported that ASNS expression is elevated in asparaginase-resistant leukemia cells compared to asparaginase-sensitive cells, and ASNS expression levels have been correlated with asparaginase sensitivity in PDAC cell lines." (PMID 38951899, 2024). "In the present study, we characterize the asparaginase and PAF-acetylhydrolase activities of purified human ASPG exploring its effect on the viability of leukemia cells." (PMID 28542249, 2017). "Amino sulfoximines directly inhibit ASNS activity, whereas asparaginase, an FDA-approved drug widely used in the treatment of leukemia, hydrolyzes asparagine to aspartate and ammonia." (PMID 26499495, 2015). "Knockdown of SOD2 induced a significant reduction in viability upon treatment with asparaginase but did not sensitize leukemic cells to other commonly used leukemia chemotherapeutic agents." (PMID 40131931, 2025). "Four-year continuous CR for leukemia patients was 68% with asparaginase treatment as compared to 55% without asparaginase treatment and toxicities were tolerable." (PMID 34868994, 2021). "The large-scale use of guinea pig serum in leukemia treatment was not possible, but in 1964 a similar tumor inhibitory effect was reported for Escherichia coli asparaginase (Mashburn & Wriston, 1964 ▸)." (PMID 34258001, 2021). "Cell viability and proliferation assays did not demonstrate any significant changes, and SOX11 knockdown did not have any impact on sensitivity to known leukemia drugs, such as dexamethasone, prednisolone, vincristine, and asparaginase." (PMID 32029838, 2020).
leukemia (continued). "Similarly, in the treatment of leukemia, the conjugation of PEG to the native asparaginase enzyme leads to fewer allergic reactions than asparaginase enzyme alone (U.S. Food and Drug Administration, 2018)." (PMID 30814951, 2019). "Transduction of UBR1 and UBR2 was sufficient to rescue leukemia cells from shSOD2-mediated sensitization to asparaginase while transduction of FBXW7 or STUB1 could not reverse this effect." (PMID 40131931, 2025). "For the other drugs tested there was very little difference in leukemia cell sensitivity in regular media compared to HPLM, except for cytarabine and asparaginase for which several, but not all, cell lines were moderately less sensitive to both drugs in HPLM media." (PMID 39099696, 2024).
pancreatitis (54 papers, 2014 to 2026). Inflammation of the pancreas. "Direct treatment-related morbidity and mortality, especially due to infections, cardio-metabolic dysfunction, hepatotoxicity, osteonecrosis and asparaginase-associated problems, such as coagulation disorders and pancreatitis, remain an important issue." (PMID 34201368, 2021). "We found the following incidence of asparaginase-associated toxicity: 24.1% clinical hypersensitivity, 19.4% hepatotoxicity, 6.7% hypertriglyceridemia, 4.2% hyperglycemia, 3.7% osteonecrosis, 3% pancreatitis, 2.4% thrombosis, and 1.2% cerebral thrombosis." (PMID 34640436, 2021). "Asparaginase-associated adverse events that led to death were hepatotoxicity (three cases), pancreatitis (one case), and cerebral thrombosis (one case)." (PMID 34640436, 2021). "Unfortunately, asparaginase causes severe toxicities such as hypersensitivity, hepatotoxicity, pancreatitis, and thrombosis." (PMID 32848787, 2020). "Three GWAS studies analyzing multiple polymorphisms showed significant associations with asparaginase-induced pancreatitis." (PMID 32848787, 2020). "(2017) assessed the association between asparaginase-induced hypersensitivity, pancreatitis, and thrombosis and polymorphisms." (PMID 32848787, 2020). "A very recent large GWAS study found and validated variants in the PRSS1-PRSS2 locus (rs4726576; rs10273639) to be associated with the risk of asparaginase-associated pancreatitis in children with ALL." (PMID 30832275, 2019). "Asparaginase-associated pancreatitis (AAP) has a reported incidence of 2 to 18% depending on the cumulative asparaginase dose (that is, treatment duration) and toxicity capture strategies but seemingly not on the route of administration." (PMID 28413626, 2017). "The results provide an insight on novel pharmacogenetic markers associated with asparaginase related allergic reactions, pancreatitis and thrombosis." (PMID 28574850, 2017). "Asparaginase-associated pancreatitis in relation to patient and disease characteristics." (PMID 40641923, 2025). "However, the role of genetic factors in relation to asparaginase treatment remains incompletely understood, partly because mutations in pancreatitis-causing genes are rarely found in pediatric ALL." (PMID 39564382, 2024). "Notably, studies indicate that reintroducing asparaginase after an initial episode of AAP carries a 40%–50% risk of a second pancreatitis episode." (PMID 39564382, 2024). "Comparison of the first and second asparaginase-associated pancreatitis episodes." (PMID 39439952, 2024). "Thus, the overall incidence of asparaginase-associated pancreatitis in children treated for ALL was 3.7%." (PMID 39123368, 2024). "In addition, GCN2 loss predisposes the pancreas to maladaptive endoplasmic reticulum (ER) stress responses and autophagy during asparaginase treatment, potentially contributing to asparaginase-associated pancreatitis." (PMID 38539506, 2024). "However, there has been limited association of increased risk of pancreatitis with any of the FDA approved asparaginase formulations." (PMID 35844739, 2022). "However, owing to recurrent asparaginase-associated pancreatitis, the patient has to abandon asparaginase in consolidation." (PMID 34160436, 2021). "Tolerance to asparaginase is linked to a favorable prognosis and the occurrence of asparaginase-induced toxicities (hepatic toxicity, hypersensitivity reactions, neutralizing antibodies, pancreatitis, thrombosis, bleeding) was comparable to that found in older children." (PMID 34359787, 2021). "Risk of pancreatitis may primarily be caused by the intense asparaginase therapy, possibly by asparaginase-induced hypertriglyceridemia; although, this remains to be demonstrated in children with ALL." (PMID 32251440, 2020). "Furthermore, a strong association was identified for rs62228256 NFATC2 and asparaginase-associated pancreatitis." (PMID 30832275, 2019).